RN7SL477P (RNA, 7SL, cytoplasmic 477, pseudogene)
Gene: Miscellaneous RNA gene on chromosome 19 (1,570,575 to 1,570,860, reverse strand). Ensembl gene ENSG00000239367.
Homologues: Orthologues: chimpanzee Metazoa_SRP (94% identical), macaque Metazoa_SRP (79% identical), pig Metazoa_SRP (72% identical). Paralogues in human: RN7SL1 (82% identical), RN7SL2 (82% identical), RN7SL3 (81% identical), RN7SL186P (79% identical), RN7SL11P (79% identical), RN7SL386P (79% identical), RN7SL126P (78% identical), RN7SL296P (78% identical), RN7SL408P (78% identical), RN7SL481P (78% identical), RN7SL664P (78% identical), RN7SL239P (78% identical), and 703 more.